ENSG00000252122
Synonyms: LOC124900382
Gene: Small nucleolar RNA gene on chromosome 16 (75,409,332 to 75,409,466, reverse strand). Ensembl gene ENSG00000252122.
Gene Ontology:
Biological process: RNA processing
Cellular component: nucleolus
Homologues: Orthologues: mouse Gm23786 (62% identical), rat LOC120100468 (62% identical), rat LOC120098405 (61% identical), rat LOC120102740 (61% identical), rat LOC120099521 (60% identical), rat LOC120096123 (59% identical), rat LOC120096832 (58% identical), mouse Gm26047 (56% identical), rat LOC120098008 (56% identical), rat Snora50d (50% identical). Paralogues in human: SNORA50C (64% identical), SNORA50D (61% identical), SNORA50B (51% identical), SNORA50A (46% identical).